APOE (apolipoprotein E)
Diseases named in the same sentence as APOE in open-access papers (continued):
Sharing a sentence is not in itself a finding about the gene and the disease.
myocardial infarction (continued). "A number of case-control studies have been conducted to clarify the association between ApoE polymorphisms and myocardial infarction (MI); however, the results are inconsistent." (PMID 25111308, 2014). "For example, a study with experimental myocardial infarction (MI) showed induction of maladaptive training of myeloid progenitors, and the trained phenotype could be transferred by bone marrow transplantation to apolipoprotein-E deficient mice on a high-fat diet." (PMID 40699210, 2025). "SRB-1 deletion in atherosclerotic ApoE knockout mice results in myocardial infarction and early death." (PMID 39336967, 2024). "They found a significant association between myocardial infarction and lipid metabolism-related gene variants, such as lipoprotein lipase (LPL), apolipoprotein E (APOE) and proprotein convertase subtilisin/kexin type 9 (PCSK9), as well as eNOS gene variants." (PMID 34564134, 2021). "We therefore tested the immunologic response to peptide stimulation of splenocyte from male apoE-/- mice fed normal chow and subjected to surgical myocardial infarction at 13 weeks of age." (PMID 30811493, 2019). "In this study, we aimed to investigate the role of apolipoprotein E in the pathogenesis of acute myocardial infarction (AMI) injury, especially its potential target, neutrophil, that takes part in ischemic injury." (PMID 31249639, 2019). "SR-B1 KO mice homozygous for a hypomorphic mutant apoE allele (hypoE) also develop HFC diet-induced coronary artery atherosclerosis, myocardial infarction, cardiac dysfunction, and reduced survival." (PMID 30356742, 2018). "Further, data on extreme groups of plasma apoE (highest 5%) versus lower levels of apoE at enrollment explores risk of IHD and myocardial infarction (MI) and is given as hazard ratios." (PMID 26937471, 2016). "These mice express very low levels of ApoE, and coupled with the knockout of the SR-B1 scavenger receptor, are a reproducible model of accelerated coronary atherogenesis and myocardial infarction when placed on a high fat diet for thirty days." (PMID 22509276, 2012). "Furthermore, apoE was found to be significantly increased in apoptotic bodies, which implies a role of apoE in the clearance of apoptotic bodies and dead tissue, like after myocardial infarction." (PMID 34575848, 2021). "In addition, survival analysis revealed that CKD/ApoE−/− mice tended to die earlier, and myocardial infarction was frequently observed at postmortem examination." (PMID 33717842, 2021). "Myocardial infarction was induced in dyslipidemic apolipoprotein E-deficient (ApoE−/−) mice with and without additional miR155 knockout by ligation of the LAD." (PMID 34067440, 2021). "Our results indicated that ApoE deficiency aggravated acute ischemic injury after myocardial infarction, but such affection was not intense enough to increase the mortality during the acute inflammatory response stage." (PMID 31249639, 2019). "However, the relationship between ApoE gene polymorphism and severity of CAD in patients with acute myocardial infarction (MI) has not been well known." (PMID 26380146, 2015). "Under typical experimental conditions, neither LDL receptor nor apoE KO mice exhibit robust occlusive coronary artery disease associated with myocardial infarction, heart dysfunction and death during the first six months of life (see for example)." (PMID 19956623, 2009). "Variations in Apolipoprotein E (APOE) and Paroxonase 1 (PON1) have been associated with Myocardial Infarction (MI) in several populations." (PMID 36980959, 2023). "Others reported that inflammation occurs at the peak in 4 days after myocardial infarction, followed by inflammation resolution and repair and that neutrophil extracellular traps (NETs, citrullinated histone 3, Cit-H3 as the readout) reach the peak at 3 days in ApoE–/– Ang II-AAA." (PMID 38327764, 2023).
myocardial infarction (continued). "It is noticeable that angina pectoris and myocardial infarction were rarely reported in LPG patients, which supports that hypothesis that the mutated ApoE still maintains anti-atherosclerotic effects although it causes LPG meanwhile based on its aggregation prone characteristics." (PMID 33663537, 2021). "SR-BI/apoE double knockout mice (dKO) fed a standard lab chow diet spontaneously develop occlusive coronary atherosclerosis, develop myocardial infarctions (MI), severe heart dysfunction and die young (mean age of 6 weeks)." (PMID 23112879, 2012). "Four weeks after myocardial infarction, the amount of smooth muscle actin (SMA)-positive myofibroblasts was significantly decreased in the infarcted area of ApoE−/−/miR155−/− mice compared to that of ApoE−/− mice." (PMID 34067440, 2021). "To investigate the role of miR155 in healing and functional recovery after myocardial infarction under dyslipidemic conditions, we induced myocardial infarction by permanent ligation of the LAD in ApoE−/− and ApoE−/−/miR155−/− mice fed a normal chow diet." (PMID 34067440, 2021). "In general, our findings reveal a critical role of apolipoprotein E in regulating Ly6G+ neutrophil activation and NET formation, resulting in limiting myocardial injury after myocardial infarction." (PMID 31249639, 2019). "Further, data in the form of hazard ratios for extreme groups of plasma apoE (highest 5%), tertiles of apoE, tertiles of apoE/HDL cholesterol ratio as well as tertiles of lipids, lipoproteins and apolipoproteins for risk of IHD and myocardial infarction (MI) is given." (PMID 26937471, 2016). "In agreement with the TTC staining data, serum levels of cTnI and CK-MB increased significantly after myocardial infarction in both ApoE−/− and WT mice compared to control groups without surgery." (PMID 31249639, 2019). "The gravest phenotype is in double knockout mice lacking scavenger receptor class B type I (SR-BI) and ApoE - the mice die of CAD induced myocardial infarction by 8 weeks of age." (PMID 21718508, 2011). "Association graphs between Pioglitazone and myocardial infarction (and Pioglitazone and Rosiglitazone) show strong associations between Pioglitazone and ADIPOQ, but not with APOE, indicating that Pioglitazone should increase HDLs but not LDLs." (PMID 22162991, 2011). "Strikingly, in contrast to the Western diet, the Paigen diet induced development of occlusive coronary arterial atherosclerosis and myocardial infarction in PDZK1/apoE dKO mice not seen in apoE KO controls." (PMID 19956623, 2009). "Myocardial infarctions, not observed in apoE KO mice (although occasional minimal fibrosis was noted), were seen in 7 of 8 dKO mice, resulting in 12 times greater area of fibrosis in dKO cardiac muscle." (PMID 19956623, 2009). "ApoE single KO mice hearts showed no myocardial infarction and only occasional, minimal amounts of fibrosis, while myocardial infarctions were observed in 7 out of 8 (88%) PDZK1/apoE dKO mice." (PMID 19956623, 2009). "However, unlike the case with Western diet feeding, we found that Paigen diet-fed PDZK1/apoE dKO, but not apoE single KO, mice were characterized by substantial occlusive coronary artery disease and the presence of myocardial infarctions." (PMID 19956623, 2009).
myocardial infarction (continued). "Similarly, IRF5 silencing via siRNA in ApoE-/- mice results in decreased M1 macrophages and accelerated wound healing after myocardial infarction, whereas transgenic absence of IRF5 gene (i.e., ApoE-/- IRF5-/- double knock-out) results in decreased necrotic core formation." (PMID 33805303, 2021).
Anxiety (104 papers, 2007 to 2025). Intense feelings of nervousness, tension, or panic often arise in response to interpersonal stresses. "ApoE-deficient mice exhibit anxiety-like behaviour in the elevated plus-maze test compared to wild-type mice." (PMID 40026711, 2025). "When genotyping FKBP5 in an AD cohort, a synergistic effect of its alleles and the APOE genotype on anxiety scores and a sex‐dependent effect of FKBP5 promoter methylation on neurophysiological brain activity has been observed." (PMID 39737748, 2025). "We found genome-wide significant signals for agitation, anxiety, apathy, delusions, and hallucinations in the APOE locus that were driven by the APOE ε4 allele." (PMID 39974048, 2025). "Our study shows that the BDNF Met allele influenced self-reported anxiety when the presence of APOE e4 and the interaction with APOE e4 was considered." (PMID 38279143, 2024). "In APOE knockout mice expressing human APOE4, enhanced measures of anxiety are associated with reduced microtubule-associated protein 2 (MAP2)-positive neuronal dendrites in the central nucleus of the amygdala." (PMID 39703925, 2024). "Contrary to the negative findings when examined separately, there seems to be an association between the BDNF Met risk allele and self-reported anxiety when controlling for the APOE e4 + and APOE*BDNF interactive effects." (PMID 38279143, 2024). "ApoE-deficient mice have increased basal adrenal corticosterone levels and abnormally increased plasma corticosterone levels after anxiety assessment using the elevated plus maze test." (PMID 37396111, 2023). "Our data suggest a synergistic effect of the stress-associated (FKBP5) and neurodegeneration-associated (ApoE) gene alleles on anxiety and the gender-dependent effect of FKBP5 on neurophysiological brain activity." (PMID 35205209, 2022). "We attempted for the first time to combine in one study the analysis of the effects of rs1360780 polymorphism in the FKBP5 gene and ε2/ε3/ε4 polymorphisms in the ApoE gene on anxiety levels and EEG parameters." (PMID 35205209, 2022). "On the other hand, several studies have reported high levels of anxiety and spatial cognitive deficits (memory loss) in apolipoprotein E (ApoE) knockout mice (ApoE−/−) compared to wild-type mice." (PMID 36077225, 2022). "Improvement in anxiety symptoms was observed in most APOE variants; however, the best responders to multifactorial intervention were APOE-3/3 (p < 0.001), APOE-3/4 (p < 0.001), and APOE-2/4 carriers (p < 0.006)." (PMID 33920985, 2021). "The authors found higher anxiety and internalizing problems scores with elevated cord blood mercury concentrations in APOE ε4 carriers compared with other APOE variants." (PMID 30626382, 2019). "In MCI patients, RNF219 and APOE variants worked together to impact the levels of anxiety negatively." (PMID 29755337, 2018). "In the study, we found that the RNF219/G variant, in synergy with the APOE-ε4 allele, amplifies the anxiety-related NPI scores." (PMID 29755337, 2018). "Additionally, the interaction observed only in APOE ε4 allele carriers between anxiety symptoms and brain Aβ burden in those with a lower DASH diet score highlights the role of genetics in this relationship." (PMID 40775676, 2025). "Furthermore, the APOE ε4 allele and anxiety symptoms remained significant after multivariate analysis." (PMID 38137059, 2023). "Moreover, compared with wild-type mice, ApoE-deficient mice showed anxiety-like behavior in the elevated plus maze test." (PMID 37396111, 2023). "In conclusion, certain genetic and affective problems, namely APOE ε4 and subclinical anxiety symptoms, were identified as risk factors of early-stage AD and may modulate brain structural marker expressions in SCD." (PMID 31159873, 2019). "Additionally it has been proposed that APOE is implicated in anxiety, but data in humans on this topic are scarce." (PMID 26175754, 2015).
Anxiety (continued). "Interestingly, the APOE e4 allele may also interact with RNF219/G variants to affect anxiety levels in women with MCI." (PMID 38473892, 2024). "Hence, there is some evidence that APOE e4 could be possibly associated with higher MBI anxiety levels among older individuals." (PMID 38473892, 2024). "Thus, we demonstrate for the first time the gender-specific effect of the rs1360780 polymorphism in the FKBP5 gene on the characteristics of the electrical activity of the brain and the development of anxiety, both influenced by the allelic polymorphism in the ApoE gene." (PMID 35205209, 2022). "Despite the smaller sample size, our results suggest that greater anxiety among Aβ+, APOE ε4 carriers may be associated with high striatal Aβ, a smaller and more specific subset of CN individuals than those who would be defined as Aβ+ by a typical binary approach." (PMID 30116029, 2020). "In summary, our data show the sex-specific effects of APOE4 on cognition and anxiety-like behavior and document sex- and APOE genotype-dependent metformin effects on memory and anxiety-related state." (PMID 39833961, 2025). "The second and stronger locus, overlapping APOE and driven by the APOE ε4 allele, was associated with multiple NPS domains, including agitation, anxiety, apathy, delusions, and hallucinations." (PMID 39974048, 2025). "As observed in this study, the age-related changes in anxiety-like behaviour in Apoeshl mice indicate that ApoE primarily influences emotional behaviour." (PMID 40026711, 2025). "In this study, we focused on the sex differences in cognitive, depressive, and anxiety- phenotypes and effects of metformin therapy in the aged apoE-TR mice." (PMID 39833961, 2025). "We found that 18-month-old apoE-TR males experienced more severe anxiety-like behaviors than their female counterparts." (PMID 39833961, 2025). "We identified genome-wide significant associations between variants in APOE and several NPS, including agitation, anxiety, apathy, delusions, and hallucinations." (PMID 39974048, 2025). "Of note, postnatal administration of an APOE receptor agonist (APOE-RA) mitigates motor learning deficits and anxiety in those mice." (PMID 38734844, 2024). "Our data also showed that postnatal administration of an APOE receptor agonist (APOE-RA) rescued both learning deficits and anxiety in PAE mice." (PMID 38734844, 2024). "Overall, these data demonstrate that decrease of APOE contributes to the motor learning deficit and anxiety behavior in PAE mice, and administration of APOE-RA positively mitigates both behavioral abnormalities." (PMID 38734844, 2024). "Paucity in data in human FASD cohort also limits our interpretation, especially APOE’s contribution in anxiety phenotypes in mice with PAE." (PMID 38734844, 2024). "In the E3-TR mice, we documented a positive relationship between plasma apoE levels and reduced anxiety measures in the open field." (PMID 36720957, 2023). "In contrast, plasma apoE levels were positively correlated with reduced measures of anxiety (i.e., increased time spent in the center) in the open field." (PMID 36720957, 2023). "When measures of anxiety were assessed in the elevated zero maze in males, there were effects of APOE, APP, and an APP × APOE interaction for the percent time spent in the open areas." (PMID 35299942, 2022). "While in males, measures of anxiety in the open field revealed an APP × APOE interaction at the 6-month time point, measures of anxiety in the elevated zero maze revealed an APP × APOE interaction at the 18-month time point." (PMID 35299942, 2022). "Individuals with SCD had an altered cortical surface area, and APOE genotype and anxiety symptoms are modified factors on the cortical surface area decrease in SCD." (PMID 31159873, 2019). "Our study revealed that, in MCI subjects, the anxiety-related NPI score depends on the interaction between APOE and RNF219 genotypes (p = 0.003)." (PMID 29755337, 2018).